INS (insulin)
Diseases named in the same sentence as INS in open-access papers (continued):
Sharing a sentence is not in itself a finding about the gene and the disease.
diabetes (continued). "After the NVBP, the DDDc difference between human insulins and insulin analugues narrowed, promoting the availability for patients with diabetes to acquire more high-quality insulin analogues." (PMID 40988682, 2025). "Intravenous (IV) insulin infusions should be initiated immediately, followed by a referral to the inpatient diabetes team at the earliest possible time." (PMID 41354385, 2025). "Characterized by persistent hyperglycemia due to defects in insulin secretion, insulin action, or both, diabetes is classified into Type 1 diabetes (T1D) and Type 2 diabetes (T2D)." (PMID 40626239, 2025). "The most common type of medical institution for treating diabetes was hospitals (61.4%), and only 12.2% of the participants used insulin." (PMID 40361844, 2025). "In PDAC donors with diabetes, INS positively correlated with both GCG and SST, suggesting a simultaneous loss of multiple endocrine cell types." (PMID 40244011, 2025). "Currently, diabetes treatment mainly relies on insulin injections, oral hypoglycemic agents, and lifestyle interventions." (PMID 39917613, 2025). "Diabetes management involves a large degree of data collection and self-care in order to accurately administer insulin." (PMID 40424579, 2025). "For diabetes management, HMNs have successfully monitored glucose levels and facilitated insulin delivery, with real-time sensing capabilities comparable to commercial glucometers." (PMID 40136911, 2025). "The model included the following baseline variables: age, diabetes duration, HbA1c, presence of microangiopathy, use of metformin, total insulin dose and duration of observation." (PMID 40277315, 2025). "Diabetes mellitus (DM) is a group of chronic metabolic disorders characterized by elevated blood glucose levels due to inadequate insulin action." (PMID 40725425, 2025). "Another study reported higher IIEF-5 scores in men treated with GLP-1 RAs versus insulin (16.7 ± 4.7 vs. 12.9 ± 6.2; p = 0.02), a difference that remained significant after adjustment for age and diabetes duration (p = 0.01)." (PMID 41008590, 2025). "Insulin adjustment in the context of type 1 diabetes mellitus was clearly defined, often only in the presence of elevated blood or urine ketones (>1.5 mmol/L) and/or blood glucose levels." (PMID 41155729, 2025). "The real-world observational study was a 7.5-year retrospective cohort study in which pre- and in-flight self-monitored blood glucose (SMBG) values were monitored in pilots with insulin-treated diabetes." (PMID 39496965, 2025). "Because most of the pancreatic beta cells have already been eliminated in cases of ICI-induced diabetes, treatment with multiple insulin injections has to be ongoing while continuing ICI treatment." (PMID 40662006, 2025). "IR is a state of decreased sensitivity and responsiveness to the action of insulin and has been identified as a hallmark of T2DM, even preceding diabetes for several years." (PMID 40415699, 2025). "Existing diabetes apps offer features that enable integrations with various devices that streamline diabetes management, such as continuous glucose monitors, insulin pumps, or regular activity trackers." (PMID 40424579, 2025). "Administration of SS‐31 has been shown to restore insulin sensitivity in the skeletal muscle of diet‐induced obese mice, underscoring the potential of mitochondrial antioxidants in diabetes management." (PMID 40599237, 2025). "Evidence indicates a pivotal role of insulin resistance within skeletal muscle and myocardium in the pathogenesis of diabetes." (PMID 39761309, 2025). "Insulin was introduced as a treatment for diabetes mellitus in the 1920s, marking a revolutionary breakthrough in the medical field." (PMID 40137145, 2025). "Many patients were middle-aged or older (58 ± 13 years), had an overweight or obese BMI (36.3 ± 9.1 kg/m2), had diabetes (85%), and received insulin therapy at home prior to admission (32%)." (PMID 40944267, 2025).
diabetes (continued). "For example, RNAi has been used to silence genes involved in insulin signalling, allowing researchers to study the effects on metabolism and diabetes." (PMID 39722550, 2025). "After 2 weeks of one‐legged HIIT, insulin‐stimulated glucose clearance in the trained leg was ∼30% higher compared with the untrained leg in both groups (stage 1: 33% and stage 2: 24% in the diabetes group; stage 1: 31% and stage 2: 29% in the controls)." (PMID 40413649, 2025). "C‐peptide has been best validated in differentiating T1D or insulin‐requiring diabetes from non‐insulin requiring diabetes." (PMID 39797595, 2025). "All the patients had diabetes diagnosed within the first 2 weeks of life, required insulin treatment, and achieved spontaneous remission in infancy." (PMID 41153775, 2025). "Diabetes mellitus represents a complicated metabolic condition marked by ongoing hyperglycemia arising from impaired insulin secretion, inadequate insulin action, or a combination of both." (PMID 39982365, 2025). "International human rights law places obligations on governments to ensure the accessibility and affordability of insulin and other components of diabetes care." (PMID 41338627, 2025). "Seventy-eight (29.7%) of patients had been diagnosed with diabetes and were on glucose-lowering agents (insulin or oral glucose-lowering agent), and 64 (82%) of them had type 2 diabetes." (PMID 40313582, 2025). "Insulin (41.6%), metformin (40.1%) and SGLT2i (30.2%) were the most commonly used diabetes medications." (PMID 41567800, 2025). "If body fat is effectively reduced by KP extract (SIRTMAX®), adipose tissue plays an important role in metabolic regulation, which can improve insulin sensitivity and contribute to the prevention of diabetes." (PMID 40661686, 2025). "Type 1 diabetes mellitus (T1DM) results from autoimmune destruction of insulin-producing pancreatic β cells, typically driven by genetic predisposition, autoimmune factors, or viral infections." (PMID 40742490, 2025). "Both groups primarily manage diabetes through a combination of insulin and oral antidiabetic treatments." (PMID 40372910, 2025). "Our study provides critical insights into the role of TSC22D1 in beta cell function, highlighting its potential as a therapeutic target to enhance insulin secretion in diabetes." (PMID 40679946, 2025). "It is envisaged that the findings will not only be of interest to key stakeholders in Ghana but also to other LMICs faced with similar challenges, with a growing prevalence of patients with diabetes requiring insulin." (PMID 39854487, 2025). "Among various treatment options for diabetes, insulin therapy remains an important approach, but it inevitably carries the risk of hypoglycaemia, particularly due to dosing errors or unexpected glucose fluctuations." (PMID 40836936, 2025). "This correlation underscores a potential association between reduced TRAPα expression and impairment of INS production, which can certainly contribute to the pathophysiology of diabetes." (PMID 40392602, 2025). "Type 1 Diabetes Mellitus (T1D) is a chronic autoimmune condition characterized by the immune-mediated destruction of insulin-producing pancreatic beta cells, resulting in insulin deficiency and persistent hyperglycemia." (PMID 41200730, 2025). "Diabetes mellitus (DM) is a group of diseases characterised by hyperglycaemia due to disrupted insulin production, reduced effectiveness of secreted insulin, or a combination of both." (PMID 39613458, 2025). "It is typically an irreversible complication due to the complete destruction of pancreatic beta cells that requires ongoing insulin treatment, and patients often exhibit labile diabetes." (PMID 41282287, 2025). "Cognitive decline is a common complication of diabetes mellitus, driven in part by oxidative stress and impaired glucose–insulin homeostasis." (PMID 40722940, 2025). "We showed that even moderately controlling diabetes with insulin use significantly reduced RifR emergence." (PMID 39937900, 2025).
diabetes (continued). "Having established the central role of lipids in insulin resistance and metabolic stress, it is crucial to delve deeper into specific lipid species that have a profound impact on diabetes pathophysiology." (PMID 40289598, 2025). "In diabetes management, oral formulation of insulin (INS) has the potential to improve safety, convenience, and patient‐centered care compared to subcutaneous injections." (PMID 40235340, 2025). "Impaired insulin action or low concentrations of insulin in insulin resistance or diabetes resulted in abnormalities in protein metabolism, reducing muscle protein synthesis." (PMID 39940262, 2025). "The genetic predisposition of beta cells to oxidative stress induced by lipotoxicity and glucose toxicity is central to the decrease of insulin secretion first and the development of diabetes." (PMID 38778593, 2025). "As the global prevalence of diabetes mellitus rises, traditional treatments like insulin therapy and oral hypoglycemic agents often fail to achieve optimal glycemic control, leading to severe complications." (PMID 39911402, 2025). "ADF also reduces blood glucose levels, increases insulin sensitivity, improves insulin resistance, and effectively alleviates type 2 diabetes mellitus in humans." (PMID 39964999, 2025). "Managing diabetes through regular insulin injections, which require precise dosing and timing to avoid serious health complications." (PMID 40294407, 2025). "This allows the individual with support from their diabetes team to adjust insulin pump settings, including glucose target range, insulin sensitivity factor, and basal rates." (PMID 39432570, 2025). "Fourteen male Wistar rats induced diabetes with streptozotocin were monitored using an continuous glucose monitoring and regulated by delivering insulin with a customized low-cost pump." (PMID 40906706, 2025). "Type 1 diabetes mellitus (T1DM) is an autoimmune disease characterized by the destruction of insulin-producing β-cells in the islets of Langerhans, accounting for approximately 5%–10% of cases." (PMID 40510419, 2025). "All forms of diabetes share the common feature of insulin dysregulation, either absolute or relative." (PMID 40244147, 2025). "Type 2 diabetes mellitus (T2DM), the most prevalent form of diabetes worldwide, results from a combination of insulin resistance and altered insulin secretion." (PMID 41208460, 2025). "Our findings revealed that as individuals age, there are several factors contributing to a decrease in insulin levels, especially in patients with both diabetes and stroke." (PMID 41383356, 2025). "These SCFAs can not only enhance insulin sensitivity and glucose metabolism but also exert potent anti-inflammatory effects, thereby contributing to diabetes prevention and management." (PMID 40906081, 2025). "High diabetes distress was also more prevalent in participants using insulin, and in those reporting a history of footulcers." (PMID 39972441, 2025). "Difficulties surrounding preparation for trips (camping, vacations) were also described, as families had to consider access to hypoglycaemia supplies for multiple people, backup diabetes technology, and even destination temperatures for insulin storage." (PMID 41051982, 2025). "Exogenous insulin is essential for diabetes management; however, subcutaneous administration is associated with discomfort, poor adherence and non-physiological peripheral hyperinsulinemia." (PMID 41471078, 2025). "Diabetes mellitus (DM) is a major metabolic and multifactorial disorder determined by chronic hyperglycemia due to insulin dysfunction, insulin secretion disorder, or both." (PMID 40997031, 2025). "Prophylactic insulin treatment in NOD mice showed a corresponding reduction in diabetes incidence, seen also in an adoptive cell transfer of diabetes." (PMID 38798081, 2025).
diabetes (continued). "Increased muscle mass improves insulin sensitivity, facilitating better glycemic control, which is essential for managing diabetes and, as shown in our trial, directly impacts morbidity and mortality of diabetic patients." (PMID 40871644, 2025). "Our results showed that exogenous insulin (ukb-b-7350) mediated OA through diabetes (ebi-a-GCST90013891) with a mediation effect of 74.26% (12.68639/ −17.08472 | | * 100%)." (PMID 41398760, 2025). "Insulin is an antidiabetic hormone, critical for regulating glucose homeostasis in individuals with diabetes mellitus." (PMID 41300526, 2025). "Oxidative stress plays a central role in the pathogenesis of diabetes and its complications by damaging pancreatic β-cells, impairing insulin signalling, and promoting systemic inflammation." (PMID 40569910, 2025). "The development of therapeutic interventions for diabetes mellitus has undergone a remarkable evolution, progressing from crude animal‐derived insulin extracts to sophisticated molecular therapies that precisely target islet hormone physiology." (PMID 40919135, 2025). "“Diabetes mellitus” is a complex metabolic disorder characterised by chronic hyperglycaemia due to defects in insulin secretion, insulin action, or both." (PMID 40481412, 2025). "In a rat model of diabetes, SC administration of insulin aspart or normal insulin resulted in a pronounced reduction in blood glucose levels over a comparatively shorter period of time (2–3 h)." (PMID 39815320, 2025). "Permanent diabetes affects a percentage of patients who will require lifelong treatment with insulin." (PMID 40003320, 2025). "The main strategy for type 1 diabetes treatment is insulin therapy, since in this type of diabetes there is an autoimmune destruction of pancreatic β cells and lack of insulin secretion." (PMID 41373413, 2025). "The combination of metformin and sodium-glucose cotransporter 2 (SGLT2) inhibitors enhances both insulin sensitivity and metabolic results among patients who have double diabetes." (PMID 40225541, 2025). "Enables the study of diabetes and glucose regulation, with potential applications in drug development for insulin production and beta-cell regeneration." (PMID 40041145, 2025). "Thirty-four studies measured diabetes as a health outcome, using either prevalence/incidence of diabetes (n = 31), glycaemic control (n = 2) and insulin resistance (n = 1)." (PMID 40447883, 2025). "This unique property, along with its biocompatibility and biodegradability, makes alginate a promising material for insulin delivery systems, which is crucial in the treatment of diabetes." (PMID 40352348, 2025). "Since its isolation and the demonstration of its glucose-lowering effects in 1921, insulin therapy has revolutionized diabetes management, particularly transforming type 1 diabetes mellitus (T1DM) from a fatal disease into a manageable chronic condition." (PMID 41303503, 2025). "Diabetes mellitus (DM) is a metabolic condition leading to chronic high blood sugar levels due to insufficient insulin production or ineffective effects of insulin on target cells." (PMID 40144552, 2025). "Regarding the pathophysiology of diabetes, it has been documented that the Asian population has predominant insulin secretory impairments; however, insulin resistance is the major cause in the Western population." (PMID 40564164, 2025). "In the event of ketosis, the pump and delivery device should be checked for malfunction and the diabetes team immediately informed so that continued pump use be reconsidered and if necessary, a temporary intermittent subcutaneous insulin regimen be employed." (PMID 39432570, 2025). "The proposed EGIR definition excluded subjects with diabetes because of difficulties in measuring insulin resistance in these individuals as beta-cell dysfunction, a key characteristic of T2DM, makes estimates of insulin sensitivity unreliable." (PMID 40217852, 2025).
diabetes (continued). "The duration of diabetes was 9.1 years in the insulin user group and 5.7 years in the non-insulin user group, indicating a more advanced disease state in those using insulin." (PMID 40564223, 2025). "Over two-thirds of DM participants (73%) were on medication for diabetes; over half (59%) on metformin and one-third on insulin (33%)." (PMID 40168299, 2025). "Current biomarkers used in clinical practice for diabetes, including glucose, hemoglobin A1c (HbA1c), insulin, C-peptide, and autoantibodies (AABs), are mainly diagnostic markers with limited prognostic value." (PMID 40056450, 2025). "Compared to the controls, the cases reported a higher rate of insulin as initiation therapy (12.14% vs 6.43%) and as their current diabetes treatment modality (37.14% vs 18.57%)." (PMID 41157992, 2025). "While commonly used by people living with type 1 diabetes mellitus, this strategy is remarkably less frequent for people living with insulin-treated type 2 diabetes mellitus (T2D)." (PMID 41313169, 2025). "The integration of CGM with information on the circadian rhythms of insulin sensitivity can lead to more precise and customized diabetes management strategies." (PMID 40649840, 2025). "The mitochondrial dysfunction and decreased insulin sensitivity in the visceral adipose tissue is a main mechanism of de novo lipogenesis which promotes liver fat accumulation in diabetes." (PMID 41335609, 2025). "Resistance of the tissues to insulin leads to increased blood glucose levels, hyperinsulinemia, β-cell dysfunction, and, finally, the development of type 2 diabetes mellitus (T2DM)." (PMID 41375221, 2025). "Type 1 diabetes mellitus (T1DM) is a chronic autoimmune disease characterized by the selective destruction of insulin-producing beta cells in the pancreatic islets of Langerhans, leading to absolute insulin deficiency." (PMID 40906116, 2025). "Impaired secretion of insulin and global insulin resistance were the central pathomechanisms of diabetes." (PMID 40356984, 2025). "This RCT was carried out in China, testing the efficacy of a clinical pharmacist-led smartphone application to improve medication adherence, insulin injection technique, and diabetes-related outcomes in a sample of women receiving insulin therapy." (PMID 39980710, 2025). "Since both insulin treatment and HbA1c are indicative of an individual’s diabetic status, this suggests that accurately predicting MI also heavily depends on the diabetes status of the individual." (PMID 40577645, 2025). "Conventional diabetes management approaches include pharmacological treatments such as insulin and oral hypoglycemic agents, as well as lifestyle changes encompassing diet and exercise." (PMID 40124248, 2025). "In current clinical practice, C‐peptide testing is recommended for classifying diabetes diagnoses, with sufficient evidence supporting the established thresholds primarily in T1D or insulin‐treated individuals." (PMID 39797595, 2025). "Participants with newly diagnosed diabetes were prescribed significantly less insulin, biguanides, sulfonylureas, thiazolidinediones and DPP4 inhibitors." (PMID 39940012, 2025). "Repeated assessment of both antibody levels and insulin secretion is crucial to avoid premature changes in diabetes classification or therapeutic strategies based solely on transient antibody elevation." (PMID 40351955, 2025). "In modern healthcare, the available pharmacological treatments for managing diabetes include insulin, insulin sensitizers, α-glucosidase inhibitors, sulfonylureas, and agents that stimulate insulin secretion." (PMID 41020901, 2025). "Following an accurate genetic diagnosis of diabetes, 19 patients switched from insulin therapy to oral agents or lifestyle interventions." (PMID 39504571, 2025). "The selection of antidiabetic agents is strongly influenced by factors such as the patient’s age and diabetes duration, which impact BMI, endogenous insulin secretion, and renal function in clinical practice." (PMID 40786473, 2025).